SP1 (Sp1 transcription factor)
Diseases named in the same sentence as SP1 in open-access papers (continued):
Sharing a sentence is not in itself a finding about the gene and the disease.
lung cancer (continued). "In the lung cancer, SIOMICS identified five shared motifs, which were similar to motifs of ZNF219, PATZ1 (MAZR), SP1, IKZF1 (Lyf-1), and the CAC-binding protein, respectively." (PMID 28684851, 2017). "Our study also provides new evidence to support the critical role of SP1 and LKB1 in the pathogenesis of HPV-related lung cancer, and suggests novel therapeutic targets." (PMID 28813465, 2017). "Our results indicate that HPV16 E6 indirectly upregulated the expression of hTERT by inhibition of LBK1 expression and upregulation of Sp1 expression, thus suggesting a HPV-LKB1-SP1-hTERT axis for the tumorigenesis of lung cancer." (PMID 28813465, 2017). "We also observed the involvement of PI3-K/Akt signaling pathway in the regulation of SP1 and EP4 in response of solamargine-inhibited lung cancer cell growth." (PMID 26689593, 2015). "For example, GemiNI analysis of a lung cancer data set with paired gene/miRNA expression (GSE18805,) identified top TFs (CREB1, SP1 and STAT3) and miRNAs (miR-15a, miR-195 and miR-497) that are dysregulated in lung cancer." (PMID 23418540, 2013). "Despite these limitations, our findings that SP1 and NFĸB inhibitors simultaneously repress ZFAS1 and restore ZNFX1 expression in lung cancer cells provide proof of concept that ZFAS1–ZNFX1 dysregulation during pulmonary carcinogenesis is potentially druggable in the clinic." (PMID 40211119, 2025). "Its dual role suggests SP1 might serve as a molecular link connecting COPD and lung cancer, where chronic inflammation in COPD may trigger abnormal SP1 activation, promoting tumor development." (PMID 40826767, 2025). "The SM may exert its anti‐lung cancer activity by dose‐dependently down‐regulates Protein kinase B (AKT/PKB) phosphorylation, SP1, NF‐κB subunit p65, and E‐prostanoid receptor 4 (EP4) in lung cancer cell lines (A549 and H1299 cells)." (PMID 39155844, 2024). "The recruitment of Sp1 was dramatically increased in NSCLC compared with normal tissues, whereas KLF6 binding was substantially reduced, suggesting that the transcription factor had changed between normal and lung cancer tissues." (PMID 35132181, 2022). "The protein levels of Sp1 and EMT-related markers, including CD44, β-catenin and ALDH1, in 51 lung cancer patients were determined by IHC and grouped them into high and low expression individually, subsequently the relationship between the survival rate and protein levels was studied." (PMID 35034634, 2022). "Next, in the older patient groups (> = 55 years), a low Sp1 level compared to a high Sp1 level was found to be related to a slightly poorer prognosis in women (HR = 2.882), but not in men (HR = 0.848), with late-stage lung cancer." (PMID 35034634, 2022). "Treatment of lung cancer cells with tobacco concentrates can lead to significant upregulation of ABCG2 and its transcription factors Sp1 and Nrf2, indicating that smoking may induce lung cancer partly through ABCG2 upregulation." (PMID 35719973, 2022). "Sp1 downregulation in late-stage but not early-stage lung cancer patients was correlated with poor prognosis (HR = 1.867)." (PMID 35034634, 2022). "Sp1 was upregulated in most of the cohorts with early-stage lung cancer (89.6%), but not in those with late-stage lung cancer (45.2%)." (PMID 35034634, 2022). "Furthermore, there was a strong inverse correlation between Sp1 and CD44 levels in clinical lung cancer specimens." (PMID 35034634, 2022). "The levels of the Sp1-regulated candidate miRNAs targeting CD44, β-catenin and ALDH1, i.e., miR-3194-5p, miR-218-5p, miR-200-5p, miR-193a-5p, miR-182-5p and miR-135-5p, were studied in A549-T24 and E2-A549 lung cancer cells." (PMID 35034634, 2022).
lung cancer (continued). "In this study, we first found that there was an inverse correlation between the Sp1 level and lung cancer prognosis in young women but not in men or menopausal women." (PMID 35034634, 2022). "Furthermore, transcription factor Sp1, a member of the zinc-finger Sp family of proteins including the Kruppel-like factor family, regulates CD147 expression in human lung cancer." (PMID 33490072, 2020). "In the present study, we confirmed that interfering of Syncytin 1 inhibited the proliferation, metastasis, and promoted apoptosis of lung cancer cells by reversing EMT pathway through a series of in vitro experiments, which was regulated by transcription factor SP1." (PMID 31397118, 2019). "Finally, in human lung cancer cells, JNK inhibited Sp1 and thereby its downstream target genes that regulate cell growth." (PMID 30995923, 2019). "Moreover, in case of lung cancer and leukaemia this interaction of miR29b with DNMT3A, DNMT3B and SP1 has already been proved." (PMID 30496316, 2018). "We previously showed that solamargine, a steroidal alkaloid glycoside extracted from the traditional Chinese herb Solanum incanum, inhibited the growth of lung cancer cells through inactivation of PI3‐K/Akt signalling pathway, followed by reducing SP1 and p65 expression." (PMID 27620163, 2017). "Only few direct transcriptional regulators of DNMT3B such as SP1, SP3 or FOXO3A have been identified and only few that are known have such a clear and important link to cancer (for example, FOXO3A negatively regulates DNMT3B promoter activity in lung cancer)." (PMID 29100357, 2017). "In conclusion, the phosphorylation of Nm23-H1 is essential for the recruitment of Nm23-H1 to the 5′UTR of Sp1 mRNA to enhance the IRES-mediated translational activity, which might contribute to the proliferation of lung cancer." (PMID 28831131, 2017). "We here demonstrated that Sp1 could remarkably enhance the ability of migration and invasion of lung cancer, and miR-29c could directly target the Sp1-3’UTR and impair the TGF-β1-induced EMT via Sp1." (PMID 27829234, 2016). "Moreover, our results illustrated the cross-talk between the SP1 and NF-κB/p65 that contributed to the solamargine-reduced EP4 expression in lung cancer cells." (PMID 26689593, 2015). "According to the results of this study, we hypothesized that inhibition of lung cancer growth by BA is through Sp1 degradation, and in contrast, that of SYK023 is through both Sp1 degradation and ER stress." (PMID 25909174, 2015). "Sp1, Sp3 and Sp4 are overexpressed in many different cancer cell lines and high expression of Sp1 in tumors is a negative prognostic factor for breast, pancreatic, gastric, glioma, prostate and lung cancer patients' survival." (PMID 26317792, 2015). "The expression of Sp1 and FOXO3 in patients with lung cancer was examined." (PMID 24519909, 2014). "The upregulated expression of Sp1 was observed in lung cancer cells than that in normal lung cells in our study (data not shown), and its binding to hTERT promoter was confirmed by pulldown assay in lung adenocarcinomas cells." (PMID 25294805, 2014). "However, depletion of miR-182 was sufficient to impair the Sp1-mediated reduction of FOXO3 expression in our experiments, suggesting that miR-182 is the major regulator of FOXO3 in lung cancer cells." (PMID 24519909, 2014). "Although studies on Sp3 and cancer are lacking, Sp1 levels have been shown to be elevated in a wide variety of cancers including breast, thyroid, hepatocellular, pancreatic, colorectal, gastric, and lung cancer." (PMID 23028678, 2012). "Inconsistent with previous findings in lung cancer, BA did not activate apoptosis or reduce the expression level of Sp1 in our research, suggesting that autophagy could play a certain role in the anticancer effect of BA." (PMID 38764025, 2024).
lung cancer (continued). "Therefore, FOXO3a and SP1, as an upstream signal of Insulin‐like growth factor binding protein 1 (IGFBP1), interacted and inhibited IGFBP1 expression in A549 and PC3 cells, exerting the growth inhibitory effect of SM on lung cancer cells." (PMID 39155844, 2024). "Sp1 transcription factor, a member of a specificity protein / Krüppel-like family, positively regulates miR-182 expression, which in turn inhibits FOXO3 translational activity and subsequently promotes the growth of cancer cells n the early stages of lung cancer progression." (PMID 37438760, 2023). "In this study, we found that E2 increased RNF4 to reduce the Sp1 level, thereby enhancing CD44 expression through downregulation of miRNAs, leading to a poor prognosis in young women with lung cancer; this finding may be beneficial for developing therapeutic strategies in the future." (PMID 35034634, 2022). "Finally, we asked whether Sp1-mediated PDSS2 repression exists and represents clinical significance in lung cancer." (PMID 31783675, 2019). "In addition, our recent studies have also indicated that the microRNA miR-182, which is induced in the late stages of lung cancer progression and binds to the 3′UTR of Sp1, could decrease Sp1 translational activity." (PMID 28831131, 2017). "Although miR-29c was reported to directly target the 3′ UTR of Sp1 to repress its expression and regulated type I collagen production under TGF-β1-stimulated kidney fibrosis, the relationship between Sp1 and miR-29c in TGF-β-induced EMT during the development of lung cancer was incompletely known." (PMID 27829234, 2016). "Furthermore, miR-29c overexpression could abrogate the tumor progression and inhibit the Sp1/TGF-β expressions in vivo, indicating that miR-29c could be a tumor suppressor and repress the Sp1/TGF-β axis-induced EMT in lung cancer." (PMID 27829234, 2016). "Interestingly, Sp1 was also decreased by BA and SYK023 in both lung cancer models." (PMID 25909174, 2015). "Furthermore, we also found that Sp1 was dramatically accumulated in the lung tissue of KrasG12D-induced lung cancer mice but not found in EGFRL858R-induced lung cancer mice." (PMID 25909174, 2015). "Furthermore, to investigate whether miR‐326 could regulate Sp1 and KLF3 expression, we transfected miR‐326 mimics into lung cancer cells and real‐time PCR results revealed that overexpression of miR‐326 suppressed the expression of Sp1 and KLF3 in both A549 and 95D cells." (PMID 30485570, 2019). "Whether Sp1 could affect the expression of KLF3 in lung cancer has never been reported." (PMID 30485570, 2019). "The activities of SP‐1 and STAT3 induced by NF‐κB, USF1, and IL‐6 were not significantly affected by K284 treatment, but lipopolysaccharide‐ and TNF‐α‐induced SP‐1, STAT3, and AP‐1 were significantly decreased by K284 treatment in A549 lung cancer cells." (PMID 34758182, 2022). "Furthermore, Kaplan–Meier survival analysis revealed that patients of lung cancer with lower expression of Sp1 and higher expression of PDSS2 exhibited the best disease-free survival, rather than higher expression of Sp1 and lower expression of PDSS2." (PMID 31783675, 2019).
hepatocellular carcinoma (107 papers, 2007 to 2026). A malignant tumor that arises from hepatocytes. "One such member of the nuclear transcription factor family, SP1 was recently identified to cause an elevation in TUG1 in hepatocellular carcinoma." (PMID 35508523, 2022). "Previous reports have shown that USP33 promotes metastasis in hepatocellular carcinoma by deubiquitinating transcription factor (SP1) and upregulating cell-surface receptor c-mesenchymal–epithelial transition factor (c-MET) expression." (PMID 40695806, 2025). "The exosome miR-21-5p in hepatocellular carcinoma cells can affect hepatocellular carcinoma cell development and patient prognosis by regulating SP1/XBP1 and promoting M2 polarization in TAMs." (PMID 40028181, 2025). "HBx transformative protein was reported to downregulate NF-κB, which prevents immune system recognition and increases the availability of Sp1, contributing to hepatocellular carcinoma (HCC) formation." (PMID 40143226, 2025). "CEBPα cooperating with Sp1 was reported to induce miR-122 expression by binding to its promoter in hepatocellular carcinoma cells, and miR-122 is a potential therapeutic target for the treatment of liver disease." (PMID 36747241, 2023). "Functionally, HBx specifically binding to VCPIP1 significantly enhanced the transcriptional transactivation of HBx by activating NF-κB, AP-1, and SP-1 and inhibited hepatoma cell clonogenicity in Huh7 and HepG2 cells." (PMID 35695579, 2022). "In contrast, serum starvation in hepatocellular carcinoma (HCC) cells increases OXCT1 expression through activation of the mTORC2-Akt-SP1 pathway." (PMID 36432618, 2022). "Taken together, Fuc-Hp production was regulated by SP1 via induction of GFT1 in the hepatoma cell line HepG2." (PMID 36313594, 2022). "This parallels with the findings on caspase-8 down-regulation in hepatocellular carcinoma, where methylation status of SP1 sites and nearby CpG dinucleotides in the promoter region were proposed to be a major regulator of caspase-8 expression." (PMID 36112666, 2022). "The TERT/SP1 interplay displays further complexity via evidence of co-activation roles on DNMT3B expression in hepatocellular carcinoma (HCC)." (PMID 33802026, 2021). "miR-363-3p was also reduced in hepatocellular carcinoma and suppressed tumorigenesis by targeting specificity protein 1 (sp1), which was in line with our prediction." (PMID 34499009, 2021). "Increased expression of hsa-miR-31-5p inhibits cell proliferation, migration, and invasion by regulating the Sp1 transcription factor in hepatocellular carcinoma." (PMID 34603447, 2021). "Secondly, Weighted_MinNetRank and MinNetRank detect rare and novel candidate driver genes (e.g., SP1 in hepatocellular carcinoma)." (PMID 33488678, 2020). "Activin A increases VEGF expression via the physical interaction of SMAD2 with the MAPK-regulated transcription factor SP1 in hepatocellular carcinoma." (PMID 32970737, 2020). "In a hepatocellular cancer model, blocking of Sp1 activity and expression with the known Sp1 inhibitor peretinoin decreased SK1 levels both in vitro and in vivo." (PMID 33171624, 2020). "For example, miR-138 targets SP1 regulated cell proliferation in hepatocellular carcinoma; SOX9 was targeted by miR-138 to regulated cell invasion in renal cell carcinoma." (PMID 31096819, 2019). "Hepatitis B virus X protein up-regulated C4b-binding protein α synthesis via activation of transcription factor Sp1 to protect hepatoma cells from attacks by complement." (PMID 31040200, 2019). "Another study investigated the role of SP1 in hepatocellular carcinoma demonstrated that SP1 regulate cystathionine γ-lyase gene expression in human hepatocellular carcinoma cell lines to promote cell proliferation and cell cycle progression." (PMID 30474556, 2018). "Our finding is consistent with our report that HBx was able to activate Sp1 in up-regulation of Lin28A/Lin28B in hepatoma cells." (PMID 27050367, 2016).
hepatocellular carcinoma (continued). "Specificity protein 1 (Sp1) transcription factor (TF) regulates expression of long non-coding RNAs (lncRNAs) in hepatocellular carcinoma (HCC) cells." (PMID 26317792, 2015). "The HDAC4/Sp1/miR-200a regulatory network responsible for the downregulation of miR-200a enhances the proliferation and migration of hepatocellular carcinoma cells." (PMID 24830600, 2014). "Inhibition of PARP-1 significantly suppressed human hepatoma cell proliferation and induced G0/G1 cell cycle arrest due to Sp1 transactivation." (PMID 24367566, 2013). "Treatment with acyclic retinoid produces a dual activation of caspase 3 and TG2 induced apoptosis of hepatocellular carcinoma cells via modification and inactivation of Sp1, resulting in reduced expression of epidermal growth factor receptor." (PMID 21214951, 2011). "LINC01134 was found to recruit the transcription factor SP1 to the p62 promoter in hepatocellular carcinoma, which in turn activates the antioxidant pathway of p62 and regulates the resistance to oxaliplatin by affecting cell viability, apoptosis, and mitochondrial homeostasis." (PMID 37914721, 2023). "Similarly, HBV genome expression is suppressed in human hepatoma HuH7-cells that are subjected to TNFα treatment or p65 overexpression, which seems to suppress SP1-mediated transcriptional activity." (PMID 36902112, 2023). "A previous report has indicated SP1 as an upstream mediator of TUG1 expression in hepatocellular carcinoma, but the significance of this interaction in regard to CRC is unknown." (PMID 35508523, 2022). "However, in the context of tumors of hepatocellular cancer, both NFY and SP1 seem to be linked to PNPase overexpression and to the outcome of patients." (PMID 36232701, 2022). "In addition, downstream transcription activators AP1 and SP1 of ERK1/2 activate the expression of KRT19 in hepatoma cells." (PMID 34659572, 2021). "The transcriptional activator role of sp1 has been verified in hepatocellular carcinoma and glioma." (PMID 34499009, 2021). "Additionally, lycopene decreases the invasiveness of human hepatoma cells by reducing the attachment capacity of NF-κB and SP-1 (specificity protein) to DNA, thus allowing the down-regulation of the matrix metalloproteinase (MMP)-9 enzyme." (PMID 32718121, 2021). "Previous studies have shown that LAMC1 is regulated by SP1 in hepatocellular carcinoma." (PMID 34218518, 2021). "Interestingly, Nrf2 promotes PDGF-A gene transcription by recruiting specificity protein 1 (Sp1) to the PDGF-A gene promoter during the progression of Hepatocellular carcinoma." (PMID 32059739, 2020). "A study in human cervical squamous carcinoma reported that miR-22-3p causes inhibition of cell apoptosis by targeting the eIF4EBP3 gene and suppresses cell proliferation in hepatocellular carcinoma and arterial smooth muscle by regulating SP1 and HMGB1, respectively." (PMID 32411089, 2020). "We suggest that loss of GSTZ1‐1 results in the accumulation of the oncometabolite SA, alkylation of KEAP1, and NRF2 activation, promoting IGF1R transcription by recruiting SP1 to its promoter, which promotes the antiapoptotic pathway of hepatoma cells in vitro and in vivo." (PMID 31267557, 2019). "Thus, we conclude that HBx is able to up-regulate C4BP through transcription factor Sp1 in hepatoma cells." (PMID 27050367, 2016). "Then, we validated that the transcription factor Sp1 might be involved in the activation of C4BP promoter stimulated by HBx in hepatoma cells." (PMID 27050367, 2016). "Interestingly, we have reported that HBx activates Lin28A/Lin28B through Sp1/c-Myc in hepatoma cells." (PMID 27050367, 2016).